ENSG00000251704
Synonyms: LOC124900535
Gene: Small nucleolar RNA gene on chromosome 2 (16,199,203 to 16,199,295, forward strand). Ensembl gene ENSG00000251704.
Gene Ontology:
Biological process: RNA processing
Cellular component: nucleolus
Homologues: Paralogues in human: SNORA40 (86% identical), SNORA40B (84% identical), SNORA40C (80% identical).